EGFR (epidermal growth factor receptor)
Diseases named in the same sentence as EGFR in open-access papers (continued):
Sharing a sentence is not in itself a finding about the gene and the disease.
tumor (continued). "While the correlation of ctDNA and efficacy of EGFR‐TKI has been extensively investigated, this work presents one of the most comprehensive ctDNA genomic analyses of tumour evolution during osimertinib treatment, which is a third‐generation EGFR‐TKI." (PMID 31393074, 2019). "The radioconjugate tumor accumulation was EGFR-specific, and PET imaging data showed a clear differentiation between xenografts with varying EGFR expression levels." (PMID 30213849, 2019). "Crosstalk between G protein-coupled receptor (GPCRs) and EGFR contributes to tumor cell progression." (PMID 30935067, 2019). "On the one hand, the EGFR signaling pathway on tumor cells is specifically blocked, leading to cell cycle arrest, reduction of tumor-cell proliferation and increase of apoptosis." (PMID 31675944, 2019). "For example, the high expression of EGFR causes the abnormal differentiation of ESCC cells and the decrease in adhesion between cells, and the tumor is prone to lymphatic and distant metastasis." (PMID 32038997, 2019). "For instance, the H1650 cell line has an abnormal activation of p-ten pathway that induces tumour growth and confers resistance to erlotinib despite the effective inhibition of the EGFR pathway." (PMID 30612556, 2019). "Epidermal growth factor receptor (EGFR; also known as ERBB1/HER1) is often expressed at higher levels in triple-negative tumours than in HR+ tumours, though expression levels vary, with up to ~ 80% of TNBC cases reported as being EGFR+." (PMID 31262335, 2019). "TAMs secrete large amounts of EGF to activate the EGF receptor (EGFR) in surrounding tumor cells, thereby supporting tumor proliferation and anoikis protection." (PMID 31096567, 2019). "The hypoxic region had significantly higher levels of EGFR than the less hypoxic region of the tumor." (PMID 31717697, 2019). "Another set of molecules involved in tumour cell growth are proteins that belong to the epidermal growth factor receptor (EGFR) family." (PMID 31198791, 2019). "A redundant MAPK signaling was also reported for tumor differentiation in EGFR-tyrosine-kinase-resistant cells upon gefitinib treatment." (PMID 32082070, 2019). "The study revealed a positive correlation between HSP90 and EGFR expression, especially in the tumor bulk." (PMID 31752169, 2019). "EGFR amplification was observed in the MGG70R-GSC-derived xenografts but not in the MGG70RR-GSC-derived xenografts, indicating that the GSC-generated xenografts preserved the EGFR status observed in the respective patient tumour specimens." (PMID 30644426, 2019). "Here, we demonstrated the feasibility and potential diagnostic value of circulating miR-504 expression in plasma to discriminate between EGFR-mutated and EGFR wild-type NSCLC, and also between EGFR-mutated and KRAS-mutated tumours." (PMID 30953094, 2019). "A mildly lower efficiency of the EGFR-retargeted ΔRGD virus compared to the EGFR-retargeted WT virus was also observed in the microfluidic tumor model." (PMID 31811202, 2019). "A combination of lysosomal activation and EGFR inhibitors produced the strongest inhibition of all tumor cells." (PMID 31717697, 2019). "Some of the genes involved include VEGFA (angiogenesis), WNT1 (proliferation), ERBB3 (proliferation), SMAD4 (tumor suppressor), NDRG2 (radioresistance) and EGFR (invasiveness) all leading to tumor aggressiveness." (PMID 30842790, 2019). "Accordingly, the duration of the response varies significantly among patients, thus suggesting that EGFR-mutant NSCLC is a heterogeneous group of tumours." (PMID 30857358, 2019). "Due to its positive anti-tumor activities in advanced NSCLC patients, especially in those with EGFR mutations, icotinib has recently been approved by the State Food and Drug Administration of China." (PMID 30953548, 2019). "Nevertheless, the results of these experiments paradoxically indicated an unexpected tumor-suppressive function of EGFR signaling in chronic colitis." (PMID 31614493, 2019).
tumor (continued). "In the patients treated with anti-EGFR antibodies, the primary tumor location was on the left side in 14 and on the right side in 3 patients (25 and 5%, respectively)." (PMID 30800219, 2019). "Immunohistochemistry results indicated that both MICAL‐L2 and EGFR were highly expressed in tumour tissues compared with matched paracancerous tissues." (PMID 31034158, 2019). "In this study, we investigated the effect of DS-1205b, a novel and selective inhibitor of AXL, on tumor growth and resistance to EGFR TKIs." (PMID 31497246, 2019). "Our male patient was an unusual case of early-stage synchronous double primary treatment-naïve EGFR-mutant NSCLC with de novo T790M and L858R mutations in each tumor." (PMID 31426797, 2019). "In contrast to standard chemotherapy, EGFR-TKIs selectively inhibit tumour cell growth by targeting the intracellular EGFR domain." (PMID 30953094, 2019). "Of note, we found that 61% of OSCC patients with EGFR+ (score of 2 and 3) tumors experienced tumor recurrence with a median progression-free survival of 13 months." (PMID 31320902, 2019). "They exhibit frequent amplifications and mutations in proto-oncogenes (EGFR, MYC, HRAS) and in cell cycle genes that drive and support tumor proliferation." (PMID 31998639, 2019). "In addition, we found that 29.0% (11/38) of patients who have discordant EGFR mutations performed their tumor tissue ARMS-PCR detection at least one months earlier than plasma ddPCR detection, suggesting that the discrepancies may be caused by molecular evolution of tumors." (PMID 31413754, 2019). "Gefitinib reversibly binds to EGFR tyrosine kinase domain and competitively inhibits ATP binding and downstream phosphorylation, thus suppressing tumor growth mediated by EGFR signaling pathway." (PMID 30911072, 2019). "Therapeutic mAbs are designed to bind with the tumor-specific antigen or oncogene proteins, such as EGFR, Her2, or CD20." (PMID 31717302, 2019). "The observed differences in EGFR expression between normal and tumor organoids were confirmed using immunohistochemistry." (PMID 31694307, 2019). "Immunofluorescence analysis of tumors showed intense staining in the MC38-EGFR5 tumor, suggesting that Erb-sumIL2 specifically targets the EGFR positive tumor." (PMID 31462678, 2019). "Patients treated with EGFR TKIs can experience a dramatic initial shrinkage of tumor followed by slow progression over several months, a finding that suggests the tumor cells remain sensitive to EGFR TKIs2,14." (PMID 31217441, 2019). "All the tumor model cells expressing EGFR were assessed in vitro, and the results showed potent cytotoxicity to LR004‐VC‐MMAE, with IC50 values of nm concentrations." (PMID 30372581, 2019). "The level of SOX2 also correlated with the tumor size and expression of epidermal growth factor receptor (EGFR) and cyclin-dependent kinase 5/6 (CDK5/6)." (PMID 31681564, 2019). "In this scenario, the epidermal growth Factor receptor (EGFR) family plays a key role in tumor growth and progression by promoting a variety of functions including proliferation, survival, invasion, and immune evasion." (PMID 31842958, 2019). "EGFR expression positively correlates with a higher tumor stage, tumor progression, and poor clinical outcomes in patients with BCa30." (PMID 31455760, 2019). "Collectively, the TEAD transcriptional output played critical functions in the pathogenesis of the EGFR-RAS-RAF-MAPK pathway and mutation-induced tumor progression." (PMID 31212916, 2019). "For example, amplifications of the EGFR gene are known to lead to tumor growth through enhancement of cell proliferation." (PMID 30957015, 2019). "EGFR plays important roles in angiogenesis and in the migration, proliferation and apoptosis of tumor cells." (PMID 30737360, 2019). "The study demonstrated that EGFR amplified CTCs are present in CTC clusters confirming that these cells are of HNC tumour origin." (PMID 30646614, 2019).
tumor (continued). "Ereg was first identified from the cultured medium of fibroblast-derived tumor cell lines and directly bound to activate EGFR, and ERBB4." (PMID 31761787, 2019). "The primary mechanism of this anti-tumor activity is the simultaneous blockade of EGFR and HER2 activation, which downregulated downstream RAS/RAF/MEK/ERK and PI3K/AKT/mTOR pathways, resulting in G0/G1 arrest in cells." (PMID 30952931, 2019). "As recently shown, PD-L1 expression in tumor cells adversely affects EGFR-TKI efficacy, especially in NSCLC patients with de novo resistance." (PMID 32082304, 2019). "Their function and impact seem to be strongly related to tumor histology and EGFR expression and signaling." (PMID 31083571, 2019). "Our results confirm that EGFR-mutant NSCLC is a heterogeneous group of tumours and, in particular, that a fraction of EGFR-mutant tumours carry additional driver mutations." (PMID 30857358, 2019). "Taken together, these results suggest that the presence of AR within the tumor microenvironment probably promotes and sustains EGFR activation, leading to drug resistance." (PMID 31370819, 2019). "The authors suggest the use of combined CRC therapies and provide evidence for the role of IGF2 as a biomarker of reduced tumor sensitivity to anti-EGFR therapy as well as a determinant of response to combined IGF2/EGFR targeting." (PMID 31623387, 2019). "Remarkably, in this 3D set-up, the transduction efficiency of targeting to the original receptor (i.e. CAR) resulted in comparable numbers of transduced tumor cells as with EGFR- and EpCAM-retargeted viruses." (PMID 31811202, 2019). "The same driven mutations (KRAS G12S in A549, EGFR L858R and T790 M in H1975) were detected in the DNA isolated from LXY30-enriched exosomes and tumor cells by polymerase chain reaction (PCR) and Sanger sequencing." (PMID 31182116, 2019). "Using cell lines and xenografts, we have previously shown that nanobody-targeted PDT is selective for cells with high EGFR expression in vitro, and induces extensive tumor damage in an in vivo HNSCC model." (PMID 31694307, 2019). "Key eligibility criteria were: basal-like BC (estrogen and progesterone receptor < 1%, HER2-negative, cytokeratin 5/6 or epidermal growth factor receptor positive by immunohistochemistry), tumor size > 2 cm or <2 cm with nodal involvement." (PMID 31398896, 2019). "In previous studies, miR-133a has been reported to directly target EGFR and thus suppressed tumor cell growth and metastasis." (PMID 30944308, 2019). "Circulating tumor cells (CTCs) were detected using CellSearch; other biomarkers (EGFR, VEGF, HER2, RAS p21, TIMP1, CAIX) by ELISA." (PMID 30783124, 2019). "Efatutazone, a third generation TZD, combined with the anti-EGFR antibody cetuximab showed synergistic activity in suppressing tumor growth in a xenograft model." (PMID 31212694, 2019). "For example, the single point mutations in the epidermal growth factor receptor (EGFRL858R) and B-Raf kinase (B-RafV600E) promote tumor formation." (PMID 30894431, 2019). "Interestingly, both the expression and mutational status of genes such as EGFR has been demonstrated to vary throughout the tumor with multiple distinct clonal populations existing in concert, many of which may have very distinct genetic and phenotypic features." (PMID 31405148, 2019). "Ongoing analysis of tumor tissue samples of the CONKO-005 trial will hopefully identify a molecular subset of pts for whom Epidermal growth factor receptor (EGFR) inhibition provides maximum benefit." (PMID 31614884, 2019). "Co-administration of an excess (15 μg) of EGF to block uptake by EGFR on hepatocytes improved tumour uptake from 2.8%ID/g to 3.9%ID/g." (PMID 31659527, 2019). "In the context of HCC, our data indicate that cadherins stabilize EGFR, and AJ complex disruption impairs EGFR stability, signaling, and tumor cell survival." (PMID 31015417, 2019).
tumor (continued). "The PI3K/Akt and MAPK signaling pathways are widely reported to participate in the regulation of PD-L1 in many tumours, and NF-kappa B was found to be involved in the EGFR-TKI induced downregulation of PD-L1 in EGFR-mutant NSCLC." (PMID 31747941, 2019). "We previously demonstrated that it is possible to use the anti-tumor antibody cetuximab to deliver an HDACi to EGFR+ tumors and these ADCs exhibited a better efficacy/toxicity ratio than either cetuximab or HDACi at their respective optimal doses." (PMID 32039017, 2019). "Collectively, the combination of YD and EGFR-TKIs shows potential for both inhibitions of in vitro cell proliferation and in vivo tumor growth via AXL degradation." (PMID 31043587, 2019). "Consistent with previous findings, our study confirmed that PARK2 exerted a tumor suppressive effect by regulating the activation of EGFR in NSCLC and inhibiting p-EGFR, p-AKT, and p-mTOR." (PMID 31508359, 2019). "Comprehensive genomic analyses of tumors from both PDX models and patients whose tumor responded to anti-EGFR antibody blockade detected mutations in ERBB2, EGFR, FGFR1, PDGFRA, and MAP2K1 as potential mechanisms of primary resistance to this therapy." (PMID 31500168, 2019). "Multiple studies have demonstrated that EGFR mutations in NSCLC are more likely to correlate with an immunosuppressive TME, the tumor mutation burden (TMB), and expression of PD-L1." (PMID 31526368, 2019). "We observed a strong correlation between EGFR expression and drug efficacy measured by tumor growth inhibition or TGI." (PMID 31331301, 2019). "LR004‐VC‐MMAE and MMAE displayed significant cytotoxicity against various tumor cells expressing EGFR, with IC50 values of 0.01–8 nm." (PMID 30372581, 2019). "As DnaJB1 positively regulates the epidermal growth factor receptors (EGFR) signaling, knockdown of DnaJB1 promotes the sensitivity of tumor cells to anti-cancer effects of the EGFR inhibitor gefitinib in human lung epithelial adenocarcinoma cells." (PMID 31878360, 2019). "EGFR is a transmembrane growth factor receptor and its downstream signaling pathways frequently contribute to tumor progression and metastasis." (PMID 31368612, 2019). "Accumulating evidence indicates that MAPK pathway contributes to the kinds of tumor physiological and biochemical progress, which is the substrate of activated EGFR." (PMID 31747939, 2019). "A further study demonstrated that the presence of KRAS mutations in ctDNA was related to disease progression, particularly in the WT tumor patients treated with anti-EGFR therapy." (PMID 31824558, 2019). "Overexpression of EGFR is a key tumor promoter and has been observed in several malignancies, especially in TNBC." (PMID 31214503, 2019). "The DNA specimens for EGFR detection are particularly important, which are typically derived from tumor tissues, peripheral blood or cell blocks in malignant pleural effusions (MPEs)." (PMID 31608233, 2019). "However, a bottleneck of all potent EGFR TKIs is the acquisition of drug resistance mutations in the catalytic pocket or other sites of the receptor, as well as secondary effects, and low ability to attenuate tumor progression, as shown by numerous laboratory and clinical studies." (PMID 31374910, 2019). "The EGFR inhibitor lapatinib or the HGFR inhibitor crizotinib alone slightly inhibited the tumor growth." (PMID 31690270, 2019). "Whereas overexpression of RICTOR reduced susceptibility of HNSCC tumor cells to PI3K inhibition, genetic ablation of RICTOR using CRISPR/Cas9 sensitized cells to PI3K inhibition, as well as to EGFR inhibition and cisplatin treatment." (PMID 31393061, 2019). "A study performed by Gule indicated that inhibition of epidermal growth factor receptor (EGFR) and VEGFR2 in ATC using vandetanib causes significant tumor growth inhibition in vivo in an orthotopic xenograft model." (PMID 30874973, 2019).
tumor (continued). "From one standpoint, a higher affinity for EGFR should translate into a greater proportion of mAb-bound EGFR; conversely, however, studies have observed that a KD between 1 and 10 nM is optimal for anti-EGFR mAb tumor targeting, accumulation, and retention." (PMID 31616627, 2019). "In vitro, upon illumination, VHH-PS conjugates selectively killed EGFR-overexpressing tumor cells with nanomolar IC50 values." (PMID 31544832, 2019). "Due to the fact, that EGFR expression is easy to examine in tumor biopsies most studies have focused on EGFR expression as a potential biomarker." (PMID 31537844, 2019). "Collectively, these results show that EGFR signaling activates PPP through 6PGD to enhance the radiation resistance of tumor cells and provide molecular basis to overcome GBM radioresistance by inhibiting 6PGD phosphorylation." (PMID 30824700, 2019). "Despite the limited ORR, the majority of patients experienced an increase in tumor doubling time, suggesting clinical benefit of combination cabozantinib and erlotinib in this heavily pretreated EGFR mutant population." (PMID 30915273, 2019). "Patients with epidermal growth factor receptor (EGFR) or activating anaplastic lymphoma kinase (ALK) genomic tumor aberrations should have disease progression on NMPA-approved therapy." (PMID 31221221, 2019). "For example, different binding affinities of various ligands for EGFR result in different levels of tumor growth in CRC cell lines." (PMID 31771279, 2019). "Our results revealed that the two distinct types of activated EGFR-specific CAR-T cells inhibited TNBC tumor growth both in vitro and in mouse models by upregulating cytokine secretion and promoting cytotoxicity in TNBC cells." (PMID 31804974, 2019). "In this study, we aimed to evaluate intrinsic and acquired resistance to anti-EGFR therapy in prospectively collected tumour samples of KRAS wt metastatic CRC (mCRC) patients who were administered cetuximab-containing regimens in real-world clinical care." (PMID 31653970, 2019). "This study aimed to investigate the potential of radiolabeled cetuximab as a non-invasive tool to predict cetuximab accumulation in NSCLC tumor xenografts with varying EGFR expression levels." (PMID 31651282, 2019). "Almost half of recurrent IDHWT tumours (43%; 3/7) harboured at least one potentially actionable variation in the genes EGFR (14%; 1/7), PTEN (14%; 1/7), BRCA1 (14%; 1/7), BRCA2 (14%; 1/7), and ATM (14%; 1/7)." (PMID 32082376, 2019). "Our findings demonstrating that erlotinib-mediated tumor regression is partially immunostimulatory are consistent with observations made with EGFR TKIs and with other targeted therapies." (PMID 31291990, 2019). "It has been reported that the EGFR is one of the important cytokines and signaling pathways involved in the survival, invasion, and proliferation of tumor cells and the related stromal cells, such as fibroblasts and neovascular endothelial cells." (PMID 31221991, 2019). "In EGFR mutant patients progressing on first- or second-generation EGFR TKI, the detection of EGFR T790M secondary resistance mutations in tumor tissue is recommended (I,A)." (PMID 30446985, 2019). "Addicted to an accelerated G1/S cell cycle progression, tumor cells with DEDD overexpression exhibit an increased susceptibility to the combinatorial treatment of cyclin-dependent kinases 4/6 (CDK4/6) and EGFR inhibitors." (PMID 31253784, 2019).